HEXB (hexosaminidase subunit beta)
Description:
Hydrolyzes the non-reducing end N-acetyl-D-hexosamine and/or sulfated N-acetyl-D-hexosamine of glycoconjugates, such as the oligosaccharide moieties from proteins and neutral glycolipids, or from certain mucopolysaccharides. The isozyme B does not hydrolyze each of these substrates, however hydrolyzes efficiently neutral oligosaccharide. Only the isozyme A is responsible for the degradation of GM2 gangliosides in the presence of GM2A. During fertilization is responsible, at least in part, for the zona block to polyspermy. Present in the cortical granules of non-activated oocytes, is exocytosed during the cortical reaction in response to oocyte activation and inactivates the sperm galactosyltransferase-binding site, accounting for the block in sperm binding to the zona pellucida (By similarity).
Synonyms: ENC-1AS; HEL-248; HEL-S-111
Tractability: Small molecule: a structure with a bound ligand is known; a high-quality ligand is known; it has a high-quality binding pocket. Antibody: its Gene Ontology location is reachable by antibodies, with high confidence; UniProt predicts a signal peptide or a membrane-spanning region. PROTAC: ubiquitination databases record sites on it; its protein half-life has been measured; a small molecule that binds it is known.
Target class: Enzyme; Hydrolase
Gene: Protein-coding gene on chromosome 5 (74,640,023 to 74,722,647, forward strand). Ensembl gene ENSG00000049860.
Subcellular location: Lysosome; Cytoplasmic vesicle, secretory vesicle, Cortical granule
Pathways (Reactome):
Metabolism: CS/DS degradation; Glycosphingolipid catabolism; Hyaluronan degradation; Keratan sulfate degradation
Disease: Defective HEXB causes GM2G2 (Hyaluronan metabolism)
Immune System: Neutrophil degranulation
Gene Ontology:
Molecular function: acetylglucosaminyltransferase activity; beta-N-acetylhexosaminidase activity; identical protein binding; protein binding; beta-N-acetylglucosaminidase activity; carbohydrate binding; hexosaminidase activity; hydrolase activity; hydrolase activity, hydrolyzing O-glycosyl compounds; protein-containing complex binding
Biological process: ganglioside catabolic process; glycosaminoglycan metabolic process; single fertilization; astrocyte cell migration; carbohydrate derivative metabolic process; carbohydrate metabolic process; chondroitin sulfate proteoglycan catabolic process; dermatan sulfate proteoglycan catabolic process; hyaluronan catabolic process; lipid catabolic process; N-acetylglucosamine metabolic process; positive regulation of transcription by RNA polymerase II; regulation of cell shape
Cellular component: azurophil granule; beta-N-acetylhexosaminidase complex; extracellular exosome; lysosome; membrane; azurophil granule lumen; cortical granule; extracellular region; lysosomal lumen; acrosomal vesicle
Genetic constraint (gnomAD): Loss-of-function variants: 21 observed, 27.61 expected, observed/expected ratio (o/e) 0.76, 90% interval 0.54 to 1.1. The upper end of that interval is the gene's LOEUF score, 1.1, which puts it in group 4 of 6, group 1 being the genes least tolerant of losing a copy. Missense variants: 325 observed, 317.57 expected, observed/expected ratio (o/e) 1.02, 90% interval 0.93 to 1.12. Synonymous variants: 156 observed, 135.01 expected, observed/expected ratio (o/e) 1.16, 90% interval 1.01 to 1.32.
Gene-disease validity (ClinGen):
ClinGen rates the evidence that HEXB causes each of these diseases.
Sandhoff disease (autosomal recessive): Definitive. A lysosomal disorder from the GM2 gangliosidosis family, caused by biallelic pathogenic variants in the HEXB gene, characterized by GM2 ganglioside accumulation in the nervous system and progressive central nervous system degeneration.
Homologues: Orthologues: chimpanzee HEXB (96% identical), macaque HEXB (94% identical), mouse Hexb (72% identical), rabbit HEXB (72% identical), dog HEXB (71% identical), rat Hexb (71% identical), pig HEXB (66% identical), guinea pig HEXB (63% identical), tropical clawed frog hexb (60% identical), zebrafish hexb (59% identical), Caenorhabditis elegans hex-1 (39% identical), Drosophila melanogaster Hexo2 (33% identical), and 2 more. Paralogues in human: HEXA (53% identical).
Diseases named in the same sentence as HEXB in open-access papers:
HEXB is named in the same sentence as 65 diseases in open-access papers, as found by Europe PMC text mining. Sharing a sentence is not in itself a finding about the gene and the disease. The quoted sentences say what the papers report.
Sandhoff disease (61 papers, 2010 to 2025). "The inability to degrade GM2 causes the severe inherited disorders Tay–Sachs and Sandhoff diseases when HEXA or HEXB genes are mutated respectively, as the residual homodimers known as HexB and HexS, respectively, are unable to hydrolyze GM2." (PMID 40608809, 2025). "Specifically, Pt2 was a heterozygous carrier for the c.1417+5G>A known pathogenic variant in HEXB, which encodes the beta subunit of the enzyme hexosaminidase that is defective in glycosphingolipidosis Sandhoff disease." (PMID 40391866, 2025). "Two patients carrying known pathogenetic GALC variants were also heterozygous for other known pathogenetic variants in other LSD‐associated genes, including HEXB (Sandhoff disease) and GUSB (mucopolysaccharidosis VI)." (PMID 40391866, 2025). "Sandhoff disease (SD) is a progressive neurodegenerative lysosomal storage disorder characterized by GM2 ganglioside accumulation as a result of mutations in the HEXB gene, which encodes the β-subunit of the enzyme β-hexosaminidase." (PMID 39791736, 2025). "The main forms include Tay–Sachs disease (TSD), caused by mutations in the HEXA gene, and Sandhoff disease (SD), caused by mutations in the HEXB gene." (PMID 41511290, 2025). "Mutations in the HEXA gene, which encodes the alpha subunit, result in TSD, whereas mutations in the HEXB gene, encoding the beta subunit, cause Sandhoff disease (SD)." (PMID 40710901, 2025). "Specifically, mutations in the HEXA and HEXB genes lead to fatal neurodegenerative diseases: Tay–Sachs disease and Sandhoff disease, respectively." (PMID 40564923, 2025). "For example, several studies have demonstrated the safety and widespread distribution of HEXA in the CNS following intracranial infusion of AAVrh8 encoding HEXA and HEXB in cats with Sandhoff disease." (PMID 36835039, 2023). "Sandhoff disease [OMIM:268800] is an AR LSD caused by mutations in the beta-hexosaminidase (HEXB) gene on chromosome 5q13." (PMID 37239976, 2023). "Mutations in the HEXA gene lead to Tay–Sachs disease, while mutations in the HEXB gene lead to Sandhoff disease." (PMID 36835039, 2023). "Sandhoff disease (SD, Online Mendelian Inheritance in Man: 268800) is an autosomal recessive lysosomal storage disorder caused by variants of the β-hexosaminidase B (HEXB) gene (Online Mendelian Inheritance in Man: 606873)." (PMID 37327298, 2023). "In our study, we identified a known variant in HEXB in one family with Sandhoff disease, and a new variant in FA2H causing ataxia with cognitive impairment." (PMID 35326432, 2022). "Sandhoff disease is caused by variants in HEXB encoding the β subunit of the enzyme hexosaminidase (HEXB)." (PMID 35326432, 2022). "Human deficiency of the β-N-acetylglucosaminidase HEXB results in the autosomal recessive lysosomal storage disorder known as Sandhoff disease with neural accumulation of GM2 gangliosides." (PMID 35967980, 2022). "For example, mutations in the human HEXB gene, which encodes a subunit of the lysosomal enzyme β-hexosaminidase, cause Sandhoff disease, which is neurodegenerative, and Hexb mRNA is a microglial marker in the mouse." (PMID 35731195, 2022). "This family of rare diseases are termed lysosomal storage diseases (LSDs) and include Gaucher disease (GBA mutations) and Sandhoff disease (HEXB mutations)." (PMID 34757540, 2022). "Sandhoff disease is caused by mutations in HEXB gene, resulting in deficiency in the activities of the enzyme Hexosaminidase A and B, and the accumulation of GM2 and GA2." (PMID 34757540, 2022). "The top 2 significant human comorbid diseases for Influenza A virus (flu) were Tay-Sachs disease (mutations in HEXA) and Sandhoff disease (mutations in HEXB) that are very similar rare genetic diseases." (PMID 36463386, 2022). "β-hexosaminidase (Hex) is an important enzyme system in human body, encoded by two genes, HEXA and HEXB, are closely related to central nervous system (CNS) diseases such as Sandhoff disease (SD) and Tay-Sachs disease (TSD)." (PMID 34422641, 2021).
Sandhoff disease (continued). "Fibroblasts obtained from two patients with Sandhoff disease with reduced enzymatic activities and confirmed HEXB mutations were studied." (PMID 34831346, 2021). "These include models deficient for GBA (e.g. modeling Gaucher disease), HEXB (e.g. Sandhoff disease) or HEXA (e.g. Tay-Sachs) or GLB1 (for GM1 gangliosidosis)." (PMID 33069254, 2020). "Sandhoff disease is one of the GM2-gangliosidoses which is caused by a mutation in the HEXB preventing the breakdown of GM2-ganglioside." (PMID 33363784, 2020). "Sandhoff disease is caused by mutations in the HEXB gene, resulting in a deficiency in both Hex A and Hex B enzymes." (PMID 33259552, 2020). "For our hexosaminidase β-subunit deficiency longitudinal study, we used a feline model of Sandhoff disease with a spontaneous mutation in the HEXB gene." (PMID 33259552, 2020). "GM2-gangliosidosis, Type II (OMIM #268800; also called as Sandhoff disease) is due to mutations in HEXB (β-hexosaminidase B), and results in deficiencies of both HexA and HexB enzymatic activities." (PMID 32351971, 2020). "Mutations in the HEXB gene cause Sandhoff disease, another variant of GM2 gangliosidosis, that similarly to Tay-Sachs, causes neurodegeneration." (PMID 32098196, 2020). "Here we generated hexb−/− zebrafish, which are β‐Hexosaminidase enzyme‐deficient, and their pathology mimics molecular, cellular and behavioral phenotypes that are also observed in HEXB‐deficient Sandhoff disease patients." (PMID 31140649, 2019). "Two of these sphingolipidoses, Tay Sachs and Sandhoff diseases, are caused by β‐Hexosaminidase (HEXB) enzyme deficiency, resulting in ganglioside (GM2) accumulation and neuronal loss." (PMID 31140649, 2019). "One LSD, Sandhoff disease, is caused by mutations in HEXB, leading to deficiencies in β‐Hexosaminidase hydrolases, formed either by HEXA/B or HEXB/B dimers." (PMID 31140649, 2019). "To create isogenic control iPS cells, we edited the genome of the Sandhoff disease iPS cells to correct the HEXB acceptor splice-site mutation." (PMID 29358305, 2018). "GLB1 mutations in GM1 gangliosidosis, HEXA mutations in Tay-Sachs disease, and HEXB mutations in Sandhoff disease were found in all, of which GLB1 c.622C>T (p.R208C) in P108 was a common mutation for patients with GM1 gangliosidosis." (PMID 29451896, 2018). "Mutations of Hexosaminidase Subunit Beta (HexB) result in the neurodegenerative gangliosidosis Sandhoff disease." (PMID 29321741, 2017). "Sandhoff disease is a severe neurodegenerative lysosomal storage disorder caused by mutations in the HEXB gene." (PMID 22848519, 2012). "Sandhoff disease (SD) is an inherited lysosomal storage disease caused by a defect of the β-hexosaminidase (Hex) β-subunit gene (HEXB) associated with deficiencies of HexA (αβ) and HexB (ββ)." (PMID 21298000, 2011). "Mutations in the HEXA gene cause Tay-Sachs disease, whereas mutations in the HEXB gene cause Sandhoff disease (SD)." (PMID 20856892, 2010). "The clinically similar disorder, Sandhoff disease is caused by the mutations in the HexB gene coding for the β-subunit of hexosaminidase A which results in simultaneous deficiency of Hex A and HexB." (PMID 20862357, 2010). "As an illustration, a published missense mutation in exon 12 of the HEXB gene causes full exon skipping and is responsible for chronic Sandhoff's disease." (PMID 20158892, 2010). "GM2 gangliosidosis is lysosomal storage disorder caused by deficiency of the heterodimeric enzyme β-hexosaminidase A. Tay-Sachs disease is caused by variants in HEXA encoding the α-subunit and Sandhoff disease is caused by variants in HEXB encoding the β-subunit." (PMID 39802759, 2024). "To test the common underlying cellular pathophysiology in GM2 gangliosidosis, we further explored the changes in Sandhoff disease, which is related to Tay–Sachs disease but due to mutations in HEXB with consequential effects on the β-subunit shared by the Hex A and Hex B isoenzymes." (PMID 34831346, 2021).
Sandhoff disease (continued). "In this study, HexA was expressly chosen to be tested as it represents the most important isoform from the biomedical point of view, inasmuch as the HEXA gene mutation is involved in both Tay-Sachs and Sandhoff diseases, contrarily to HexB, which is only involved in Sandhoff disease." (PMID 34064736, 2021). "Sandhoff disease is caused by mutations in the HEXB gene that encodes the β-subunit of either the β-hexosaminidase (HEXB: two β-subunits) or α-hexosaminidase (HEXA: one β- and one α-subunit) enzyme, while Tay-Sachs disease involves mutations in HEXA, which encodes the α-subunit of HEXA." (PMID 32435656, 2020). "Sandhoff disease is caused by mutations in HEXB, a gene that encodes the beta subunit of β-hexosaminidase, leading to storage of GM2 ganglioside and other glycoconjugate substrates in the central nervous system (CNS), resulting in progressive neurodegeneration, CNS inflammation and premature death." (PMID 32276303, 2020). "Sandhoff disease (SD)(MIM 268800) is an autosomal recessive lysosomal lipid storage disorder caused by biallelic variants within the HEXB gene, resulting in deficiency of HEXA and HEXB enzymes and intralysosomal accumulation of GM2 ganglioside and related glycolipids within neurons." (PMID 31852446, 2019). "We identified a homozygous splice site variant (NM_000521:c.445 + 1G > T) in the hexosaminidase B (HEXB) gene confirming a diagnosis of Sandhoff disease (SD; type II GM2-gangliosidosis), an autosomal recessive lysosomal storage disorder caused by deficiency of hexosaminidases in a single family." (PMID 31852446, 2019). "Hypomyelination was reported in several LSDs, including GM1 gangliosidosis with deficiency in acid β-galactosidase due to GLB1 mutations, and GM2 gangliosidosis with deficiency in β-hexosaminidase A (Tay-Sachs disease, HEXA mutations) or β-hexosaminidases A and B (Sandhoff disease, HEXB mutations)." (PMID 29451896, 2018). "We also found different mutations in the HEXA and HEXB genes and that the most common mutation in HEXB was c.1597C>T, which suggests that screening the HEXB gene for this prevalent mutation is a cost-effective test in individuals with suspicion of having Sandhoff disease." (PMID 31428437, 2018). "The infantile Sandhoff disease patient was identified as compound heterozygous for HEXB mutations." (PMID 29358305, 2018). "In addition, Sandhoff disease is a related LSD that arises from mutations in the β-subunit of the lysosomal enzyme β-hexosaminidase (HEXB) with a resultant accumulation of GM2 gangliosides in the endolysosomal compartment and severe neuronal degeneration." (PMID 26467605, 2016). "Mutations in the HEXA gene encoding the α-chain of (β-hexosaminidase-A) Hex-A leads to Tay-Sachs disease or B variant, while mutations in the β-chain encompassing HEXB gene leads to deficiency of both Hex-A and Hex-B (total-Hex) causing Sandhoff disease or O variant." (PMID 27402091, 2016). "Sandhoff disease (SD) is a lysosomal disorder caused by mutations in the HEXB gene." (PMID 22848519, 2012). "Sandhoff disease (SD) results from mutations of the HEXB gene." (PMID 22848519, 2012). "TSD and Sandhoff disease are lysosomal storage disorders caused by mutations in the HEXA and HEXB genes, encoding the α and β subunit, respectively." (PMID 41026525, 2025). "Sandhoff disease (SD), a GM2 gangliosidosis disorder, is a rare, autosomal recessive, prematurely fatal lysosomal storage disease (LSD) caused by mutations in HEXB, which encodes the β subunit of β-hexosaminidase." (PMID 39791736, 2025). "Previous studies have indicated that, in the Ids-deficient mice, there is a marked elevation of β-hexosaminidase (HEXB)—a lysosomal enzyme responsible for Sandhoff disease—in the body." (PMID 38053930, 2023).
Sandhoff disease (continued). "Intracerebroventricular (ICV) injections of a modified HexB, with both HexA and HexB activities, into Sandhoff’s disease mouse models showed marked reductions in GM2 and a two-fold increase in Hex activity, as well as an observed reduction of GM2 in the liver." (PMID 35865957, 2022). "GM2 gangliosidoses include the Tay-Sachs disease, the Sandhoff disease, and the GM2 AB, which result from LoF mutations in the genes HEXA, HEXB, and GM2A, respectively." (PMID 34690692, 2021). "The GM2 gangliosidoses (GM2), Tay-Sachs and Sandhoff diseases, are rare, autosomal recessive genetic disorders caused by mutations in the lysosomal enzyme β-hexosaminidase A (HEXA) or β-hexosaminidase B (HEXB) genes, respectively." (PMID 32295606, 2020). "To demonstrate that the β-hexosaminidase deficiency was responsible for the increased size of the Sandhoff disease organoids, we injected the organoids with AAV carrying monkey HEXA and HEXB genes (AAV-HEXA/B) to restore expression of β-hexosaminidase." (PMID 29358305, 2018). "In Sandhoff disease, structure-based approaches like SWISS-MODEL, COTH, and Mutation Taster have similarly been used to assess the structural consequences of Hexosaminidase Subunit Beta (HEXB) mutations." (PMID 41249457, 2025). "Gene ontology analysis of the top 100 upregulated and top 100 downregulated genes for HEXB-corrected organoids compared with Sandhoff disease organoids revealed that the top biological process pathways identified were predominantly associated with central nervous system and neuronal differentiation." (PMID 29358305, 2018). "Hexosaminidase subunits alpha and beta (HEXA and HEXB) form a glycosyl hydrolase in lysosomes and catalyze the degradation of the ganglioside GM2, and loss-of-function mutations in these genes lead to Tay–Sachs disease (GM2-gangliosidosis type I) and Sandhoff disease (GM2-gangliosidosis type II)." (PMID 36411275, 2022). "Three LSDs associated with GM2-gangliosidosis are Tay-Sachs disease (TSD, OMIM #272800), Sandhoff’s disease (SD, OMIM #268800), and GM2 activator protein deficiency (also called AB variant, OMIM #272750), and are associated with pathogenic variants in HEXA, HEXB, and GM2A, respectively." (PMID 35865957, 2022). "There are no evidences of a link between HEXB deficiency and PD, however, several case reports describe the manifestation of parkinsonian motor symptoms in patients with either childhood- or adult-onset Sandhoff disease." (PMID 32098196, 2020). "Subsequently, AAVrh8 vectors were employed to co-deliver HEXA and HEXB in a 1:1 ratio into the thalamus and DCN, yielding prolonged survival in a Sandhoff disease feline model." (PMID 39559557, 2024). "Bilateral injection of AAV1 carrying HEXA and HEXB into the deep cerebellar nuclei (DCN) and thalamus has significantly prolonged the lifespan of Sandhoff disease mouse and feline models." (PMID 39559557, 2024). "Tay-Sachs disease (TSD) and Sandhoff disease are fatal neurodegenerative diseases without an effective therapy that are caused by mutations in the HEXA and HEXB genes, respectively." (PMID 41026525, 2025). "Furthermore, we identified several DSH cats with GM2 gangliosidosis variant 0 (Sandhoff disease, OMIA 001462-9685), all of which were homozygous for a nonsense mutation (HEXB:c.667C>T)." (PMID 40869986, 2025).